LAPTM4B (lysosomal protein transmembrane 4 beta)
Diseases named in the same sentence as LAPTM4B in open-access papers (continued):
Sharing a sentence is not in itself a finding about the gene and the disease.
leukemia (6 papers, 2019 to 2026). A malignant (clonal) hematologic disorder, involving hematopoietic stem cells and characterized by the presence of primitive or atypical myeloid or lymphoid cells in the bone marrow and the blood. "In leukemia, LAPTM4B was expressed in stem cells and associated with specific subtypes." (PMID 40092987, 2025). "We found that genes associated with HSCs and leukemia stem cells (LSCs) were up-enriched in high LAPTM4B expression samples, as well as genes associated with cell cycle, DNA replication, MYC target, E2F and G2M checkpoint pathways were also up-enriched in in Ph+ B-ALL." (PMID 40092987, 2025). "Many leukemia stem cell like genes of the LSC17 signature diminished after day 14 such as LAPTM4B, MMRN1, ADGRG1 or AKR1C3, but some were upregulated again by day 30, day 70 CD19- and/or day 70 CD19+." (PMID 41145673, 2026). "Then, we found that LAPTM4B is expressed primarily in stem cells at single-cell level in leukemia, and highly expressed in BCR/ABL subtype of B-ALL, and upregulated stem cell pathway in Ph+ B-ALL." (PMID 40092987, 2025). "We observed upregulation of both KDM6B and LAPTM4B in EVI1hi leukemia cells compared with EVI1lo leukemia cells." (PMID 39680456, 2024). "The EVI1/KDM6B/H3K27me3/LAPTM4B signaling pathway was also identified in EVI1hi human leukemia cell lines." (PMID 39680456, 2024). "We found that hyperactivation of the LAPTM4B-driven mTOR pathway was crucial for the growth of EVI1hi leukemia cells." (PMID 39680456, 2024). "Moreover, KDM6B inhibitor and LAPTM4B knockdown significantly inhibited growth and induced apoptosis of EVI1hi leukemia cell lines." (PMID 39680456, 2024). "In addition, LAPTM4B stimulated the mTOR pathway in EVI1hi leukemia cells." (PMID 39680456, 2024). "Although there is no direct evidence that links LAPTM4B to leukemia, its upregulation has been shown to implicate PI3K/AKT signaling and ubiquitination pathways, both with crucial roles in leukemogenesis." (PMID 30753220, 2019).
lung adenocarcinoma (5 papers, 2015 to 2026). A carcinoma that arises from the lung and is characterized by the presence of malignant glandular epithelial cells. "To assess the dynamic regulation of LAPTM4B during the acquisition of drug resistance, we collected matched tumor tissues from six patients with histologically confirmed lung adenocarcinoma, all carrying EGFR 19Del mutations." (PMID 41362742, 2026). "Moreover, our results have also found that the serum level of LAPTM4B was significantly associated with the tumor progression and treatment effects of lung adenocarcinoma." (PMID 36506911, 2022). "Similar to our previous findings of declined serum LAPTM4B levels in postchemotherapy samples in lung adenocarcinoma, serum LAPTM4B levels were significantly decreased in BC patients after adjuvant therapy." (PMID 36506911, 2022). "Based on the previous studies, we explored the biological role and clinical significance of LAPTM4B in lung adenocarcinoma." (PMID 30940109, 2019). "This study was to determine the clinical significance and biological roles of LAPTM4B in lung adenocarcinoma (LAC)." (PMID 30940109, 2019). "Similarly, LAPTM4B knockdown suppressed the proliferation of lung adenocarcinoma cells through the PI3K/AKT signal pathway." (PMID 32558212, 2020). "Therefore, our results indicated that LAPTM4B may be identified as a valuable serum biomarker for diagnosis and treatment of lung adenocarcinoma." (PMID 30940109, 2019).
endometrial cancer (4 papers, 2013 to 2025). Primary or metastatic malignant neoplasm involving the endometrium (mucous membrane that lines the endometrial cavity). "Of note, LAPTM4B was also closely associated with ovarian, cervical, and endometrial cancers." (PMID 32651973, 2021).
nasopharyngeal carcinoma (4 papers, 2019 to 2025). A carcinoma arising from the nasopharyngeal epithelium. "The impact of LAPTM4B on the malignancy of nasopharyngeal carcinoma (NPC) remains unclear." (PMID 32651973, 2021).
osteosarcoma (4 papers, 2020 to 2025). A usually aggressive malignant bone-forming mesenchymal neoplasm, predominantly affecting adolescents and young adults. "Moreover, our data revealed that LAPTM4B expression was markedly associated with the clinical‐pathological features, including tumor size (P = 0.004*) and clinical stage (P = 0.035*), of patients with osteosarcoma." (PMID 32558212, 2020). "Our results further demonstrated that ablation of LAPTM4B obviously blocked the proliferation and invasion of osteosarcoma cells in vitro and restrained tumor growth and metastasis in mice." (PMID 32558212, 2020). "We determined the significance between LAPTM4B and clinical features, including the tumor size (P = 0.004*) and the clinical stage (P = 0.035*) of osteosarcoma patients." (PMID 32558212, 2020). "In summary, we demonstrated that LAPTM4B was highly expressed in osteosarcoma tissues and correlated with the clinical pathological features." (PMID 32558212, 2020). "Our data further confirmed through transwell assays and lung metastasis assays, respectively, that LAPTM4B regulated cell invasion and tumor metastasis of osteosarcoma." (PMID 32558212, 2020). "Performing colony formation assays, we found that the proliferation of osteosarcoma cells was dramatically inhibited as a result of LAPTM4B shRNA transfection." (PMID 32558212, 2020). "As we previously found, LAPTM4B affected the proliferation and invasion of osteosarcoma cells in vivo." (PMID 32558212, 2020). "Immunohistochemical (IHC) assays were performed to detect the expression levels of LAPTM4B in 62 tissue samples of osteosarcoma tissues and corresponding non‐tumor tissues." (PMID 32558212, 2020). "According to LAPTM4B staining intensity in tumor tissues, osteosarcoma patients were classified into LAPTM4B high expression and low expression groups." (PMID 32558212, 2020). "We investigated the potential involvement of LAPTM4B in osteosarcoma progression and confirmed LAPTM4B as a novel therapeutic target for osteosarcoma." (PMID 32558212, 2020). "In conclusion, all these results confirmed that LAPTM4B has a critical role in the growth and metastasis of osteosarcoma." (PMID 32558212, 2020). "We then explored the effects of LAPTM4B on osteosarcoma cell proliferation through colony formation assays." (PMID 32558212, 2020). "We therefore found that LAPTM4B ablation remarkably blocked osteosarcoma cell proliferation and invasion and restrained tumor growth and metastasis in mice." (PMID 32558212, 2020). "We found high expression of LAPTM4B in 62 human osteosarcoma tissues." (PMID 32558212, 2020). "We revealed that LAPTM4B was highly expressed in human osteosarcoma tissues." (PMID 32558212, 2020). "Notably, we found that LAPTM4B was mainly located in the cytoplasm of tumor cells and highly expressed in osteosarcoma tissues compared with adjacent non‐tumor tissues." (PMID 32558212, 2020). "We here revealed the high expression of LAPTM4B in human osteosarcoma tissues, and its expression level was obviously correlated with the clinical pathological features (including tumor size and clinical stage) of patients who underwent osteosarcoma." (PMID 32558212, 2020). "We found that LAPTM4B was correlated with the clinical features and could promote the progression of osteosarcoma, although the mechanism remains unclear." (PMID 32558212, 2020). "Therefore, we sequentially detected the effects of LAPTM4B ablation on the invasion of osteosarcoma cells through transwell assays." (PMID 32558212, 2020). "Given the complexity of the LAPTM4B function, we should next explore whether LAPTM4B could regulate osteosarcoma development in a different manner, such as a lysosome‐dependent manner." (PMID 32558212, 2020). "Notably, we here identified that a member of the LAPTM family, LAPTM4B, has the potential to become a therapeutic target for osteosarcoma." (PMID 32558212, 2020).
osteosarcoma (continued). "Interestingly, we found high expression levels of LAPTM4B in human osteosarcoma tissues and explored the potential correlations between LAPTM4B expression levels and clinical pathological characteristics (tumor size and clinical stage) of patients with osteosarcoma." (PMID 32558212, 2020). "In addition, LAPTM4B facilitates the growth and metastasis of osteosarcoma cells in mice." (PMID 32558212, 2020). "LAPTM4B could, therefore, provide a novel and promising therapeutic target for osteosarcoma." (PMID 32558212, 2020). "We therefore hypothesize that LAPTM4B regulates osteosarcoma cell proliferation in a similar way." (PMID 32558212, 2020).
renal cell carcinoma (3 papers, 2023 to 2025). "In this study, LAPTM4B content was detected using the urine survivin method, and was used to construct a diagnostic model of renal cell carcinoma with an AUC of 0.920." (PMID 36937841, 2023). "To investigate the role of LAPTM4B in renal cell carcinoma, we performed experiments to detect the proliferation of ccRCC cells after LAPTM4B knockdown." (PMID 36937841, 2023). "Downregulation of LAPTM4B expression significantly reduced the proliferation of renal cell carcinoma cells and promoted cell apoptosis through cell experiments." (PMID 36937841, 2023). "Subsequently, we confirmed the differential expression of LAPTM4B in renal cell carcinoma of different Fuhrman grades using western blotting." (PMID 36937841, 2023).
viral infection (3 papers, 2012 to 2025). "Mutations in LAPTM4B (Lysosomal Protein Transmembrane 4 Beta) gene, may impair endosomal network, eventually compromising productive viral infection." (PMID 33206719, 2020). "The median expression of some genes (CTBP1, LAPTM4B, CFAP45, DSC2, LAMP1, EXOG, RPS21, and SIRPB1) was higher in bacterial compared to viral infection." (PMID 41496780, 2025). "We found that genotype *2 of the LAPTM4B gene was significantly associated with recurrence, poor histopathologic differentiation, higher TNM stage and portal vein invasion (P<0.05), but not with viral infection status, tumor size or serum AFP level, age or gender (P>0.05)." (PMID 22509374, 2012).
diabetes (2 papers, 2022). "CD36, a fatty acid transporter, was previously shown to be associated with diabetes, while the role of LAPTM4B and RCOR1, significantly dysregulated in δ-cells, remains unclear and requires further investigation." (PMID 35885959, 2022).
esophageal cancer (2 papers, 2016 to 2025). A primary or metastatic malignant neoplasm involving the esophagus. "The present study aimed to identify the association of LAPTM4B genotype with clinicopathological features and prognosis in colorectal and esophageal cancer patients." (PMID 27391361, 2016). "In our study, the LAPTM4B *2 allele frequency rate are 33.3%, 27.8% and 23.8%, nearly the same as previous report in colon, rectal and esophageal cancers, respectively." (PMID 27391361, 2016). "The present study aimed to investigate whether there is a correlation of LAPTM4B gene polymorphism with prognosis in colorectal and esophageal cancer patients after surgical resection." (PMID 27391361, 2016). "However, there was no report about the association between the existence of two variant alleles of LAPTM4B with the prognosis in patients with colorectal and esophageal cancers." (PMID 27391361, 2016). "Correlation of Distribution of various genotypes of LAPTM4B with clinicopathological parameters in colorectal and esophageal cancer patients." (PMID 27391361, 2016). "There was not a relationship between LAPTM4B genotype and other clinical factors in colorectal and esophageal cancer patients." (PMID 27391361, 2016).
glioma (2 papers, 2019 to 2026). A benign or malignant brain and spinal cord tumor that arises from glial cells (astrocytes, oligodendrocytes, ependymal cells). "Preclinical data link LAPTM5 to stroke outcomes via stress-kinase and lysosomal pathways, while LAPTM4A and LAPTM4B associate with glioma progression, immune evasion, and therapy resistance." (PMID 41666016, 2026).
head and neck squamous cell carcinoma (2 papers, 2019 to 2021). A squamous cell carcinoma that arises from any of the following anatomic sites: lip and oral cavity, nasal cavity, paranasal sinuses, pharynx, larynx, and salivary glands. "LAPTM4B mRNA is upregulated more than 3-fold in head and neck squamous cell carcinoma tissues (HNSC) relative to normal tissues." (PMID 32651973, 2021). "Expression patterns and effects of LAPTM4B-35 on head and neck squamous cell carcinomas (HNSCC) are unknown." (PMID 31827181, 2019).
lentivirus infection (2 papers, 2019 to 2023). Virus diseases caused by the Lentivirus genus. "After 3 days of shRNA lentivirus infection, the expression of LAPTM4B was confirmed by qRT-PCR and western blotting assays; results showed the expression of LAPTM4B to obviously be decreased in shLAPTM4B cells than in shCtrl cells." (PMID 36937841, 2023). "Then, we constructed LAPTM4B stably overexpressing A549 cells by lentivirus infection and endogenously knocking down LAPTM4B in HCC827 cells by specific siRNAs transfection." (PMID 30940109, 2019).
myeloid malignancies (2 papers, 2021 to 2024). "The most important variables in the model were age and the expression of KDM5B and LAPTM4B, two genes previously associated with the biology and prognostication of myeloid neoplasms." (PMID 33854980, 2021). "Our findings highlight the presence of the EVI1/KDM6B/H3K27me3/LAPTM4B signaling axis in EVI1-overexpressed myeloid malignancies and suggest the therapeutic potential of inhibition of the KDM6B/H3K27me3/LAPTM4B signaling axis in patients with EVI1hi malignancies." (PMID 39680456, 2024).
acute B cell lymphoblastic leukemia (1 paper, 2025). "Building upon the reported biological functions of lysosomal membrane-associated protein transmembrane-4 beta (LAPTM4B) in existing studies, we aim to comprehensively understand its involvement in cancer, especially Philadelphia chromosome-positive acute B cell lymphoblastic leukemia (Ph+ B-ALL)." (PMID 40092987, 2025). "We aimed to study the effect of the LAPTM4B gene in pan-cancer and Philadelphia chromosome-positive acute B cell lymphoblastic leukemia (Ph+ B-ALL)." (PMID 40092987, 2025).
acute myeloid leukemia (1 paper, 2019). Acute myeloid leukemia (AML) is a group of neoplasms arising from precursor cells committed to the myeloid cell-line differentiation. "Differential expression of LAPTM4B and MIR155HG was confirmed in a small cohort of young adult NPM1-mutated cytogenetically normal acute myeloid leukemia (CN-AML) patients." (PMID 30753220, 2019).
benign breast disease (1 paper, 2022). "Serum LAPTM4B level was evaluated in 426 BC patients, 40 benign breast disease, and 80 healthy controls by ELISA." (PMID 36506911, 2022). "The LAPTM4B level in the BC group was significantly higher than benign breast disease and healthy controls." (PMID 36506911, 2022). "The results showed that LAPTM4B was markedly increased in sera from BC patients compared with benign breast disease and normal controls." (PMID 36506911, 2022).
chondrosarcoma (1 paper, 2023). A malignant cartilaginous matrix-producing mesenchymal neoplasm arising from the bone and soft tissue. "Sarcoma includes OS, chondrosarcoma, Ewing sarcoma, synovial sarcoma, leiomyosarcoma, and so on, the detailed expression of LAPTM4B in these cell lines was analyzed." (PMID 37147294, 2023).
chronic atrophic gastritis (1 paper, 2015). Atrophic gastritis that is persistent and long-standing. "According to the immunohistochemical staining assessment and scoring criterion, all the normal gastric mucosa and mucosa diagnosed as chronic atrophic gastritis (without intestinal metaplasia and dysplasia) showed negative expression of LAPTM4B-35." (PMID 25689860, 2015). "No expression of LAPTM4B-35 was found in normal gastric mucosa and chronic atrophic gastritis without intestinal metaplasia and dysplasia." (PMID 25689860, 2015).
chronic gastritis (1 paper, 2015). Inflammation of the stomach that is chronic in nature. "There were 3 cases with LAPTM4B-35 positive expression among the 10 cases diagnosed as chronic gastritis with intestinal metaplasia, and 6 cases with LAPTM4B-35 positive expression among the 10 cases diagnosed as chronic gastritis with dysplasia." (PMID 25689860, 2015). "The LAPTM4B-35 expression rate was 30% in chronic gastritis with intestinal metaplasia, 55% in intestinal metaplasia beside cancer tissues, 60% in dysplasia, peaking at 90.4% in GC." (PMID 25689860, 2015).
chronic obstructive pulmonary disease (1 paper, 2023). A chronic and progressive lung disorder characterized by the loss of elasticity of the bronchial tree and the air sacs, destruction of the air sacs wall, thickening of the bronchial wall, and mucous accumulation in the bronchial tree. "Studies have shown that alterations in the expression of LAPTM4B are associated with various lung diseases, including chronic obstructive pulmonary disease (COPD) and idiopathic pulmonary fibrosis (IPF)." (PMID 37250098, 2023).
COVID-19 (1 paper, 2020). A disease caused by infection with severe acute respiratory syndrome coronavirus 2. "We also identified two additional genes, PRKRA and LAPTM4B, for which the probability of observing a deleterious variant was computed higher in the COVID-19 samples compared to controls." (PMID 33206719, 2020).
invasive ductal carcinoma (1 paper, 2022). "However, there were significant associations between LAPTM4B levels and classic variables including age (p = 0.020), histological type (invasive ductal carcinoma, IDC) (p = 0.021), TNM stage (p = 0.001), nodal metastasis (p < 0.001), distant metastasis (p = 0.001), and Ki-67 status (p = 0.034)." (PMID 36506911, 2022).
lung diseases (1 paper, 2023). "LAPTM4B, also known as Lysosomal-associated protein transmembrane 4 beta, has been associated with various lung diseases." (PMID 37250098, 2023). "LAPTM4B was the only gene with significant interaction among lung disease, ethnicity, and sex, with fold change greater than two." (PMID 37250098, 2023).
lysosome disorder (1 paper, 2025). "In the present study, we found that Ba significantly reversed the ER-lysosome disorder triggered by Cu exposure by targeting LAPTM4B." (PMID 40887645, 2025).
oral cavity carcinoma (1 paper, 2019). A carcinoma arising in the oral cavity. "In oral cavity carcinoma, expression of LAPTM4B-35 had no influence on OS (p = 0.4167 [Log Rank], p = 0.5947 [Gehan-Breslow]) or DFS (p = 0.7432 [Log Rank], p = 0.9303 [Gehan-Breslow])." (PMID 31827181, 2019).
oropharyngeal carcinoma (1 paper, 2019). Carcinoma, predominantly squamous cell, arising from the epithelial cells of the oropharynx. "In oropharyngeal carcinoma, high expression of LAPTM4B-35 almost correlated with a statistically significant worse DFS (p = 0.0545 [Log Rank], p = 0.0856 [Gehan-Breslow])." (PMID 31827181, 2019). "The analysis showed that patients with HPV positive oropharyngeal cancer and a high LAPTM4B-35 expression had a significantly worse DFS." (PMID 31827181, 2019). "We therefore correlated expression of LAPTM4B-35 with survival data of each anatomical region and HPV status in oropharyngeal carcinoma." (PMID 31827181, 2019).
oropharyngeal tumours (1 paper, 2019). "LAPTM4B-35 was highly expressed in 33.3% of HPV positive oropharyngeal tumours and 41.9% of HPV negative tumours." (PMID 31827181, 2019).
prostate adenocarcinoma (1 paper, 2025). "While, low LAPTM4B expression was observed in 4 cancer types, Pan-kidney cohort (KIPAN), prostate adenocarcinoma (PRAD), kidney renal clear cell carcinoma (KIRC), and kidney chromophobe (KICH)." (PMID 40092987, 2025).